USP15 (ubiquitin specific peptidase 15)
Diseases named in the same sentence as USP15 in open-access papers (continued):
Sharing a sentence is not in itself a finding about the gene and the disease.
tumor (continued). "Our previous analyses of GBM datasets have pointed to the de-ubiquitinase USP15 as a candidate tumor suppressor gene for GBM based on gene expression and gene CNV patterns." (PMID 29299163, 2017). "It has been recently demonstrated that inhibition of USP15 both induced tumor cell apoptosis and boosted antitumor T cell responses, and thus have important clinical applications." (PMID 28074857, 2017). "It has been reported that the reduced RBM5 and USP15 expressions result in tumor cell proliferation and induce tumor cell apoptosis, respectively." (PMID 26897165, 2016). "Hence, the role of USP15 as either an oncogene or a tumor suppressor in NSCLC remains an intriguing area of study." (PMID 40762380, 2025). "This discrepancy may reflect the context‐dependent nature of USP15 function, which could vary depending on the tumor subtype, cellular environment, or interaction partner." (PMID 40762380, 2025). "We thus wonder whether USP15 functions in tumor formation partially through its regulation of TBX3 expression." (PMID 38750011, 2024). "Next, we wondered whether the continuously increased Usp15 through mPTC progressing induced by genetic BRAFV600E incorporation was a tumor cell autonomous behavior." (PMID 38750011, 2024). "These analyses indicate that high USP15 expression level could predict higher tumor progression and poorer overall survival, in BRAFV600E related malignancies, presumably due to its regulatory function on TBX3 protein homeostasis." (PMID 38750011, 2024). "Interference with USP15 expression reversed tumor progression and distal colonization in vivo." (PMID 39164728, 2024). "Interfering with USP15 expression reversed tumor progression and distal colonization in vivo." (PMID 39164728, 2024). "To assess whether tumor development was due to Usp15 loss of heterozygosity, we used fluorescence-activated cell sorting (FACS) to isolate tumor cells from Usp15 homozygous, heterozygous and wild-type KRasG12D tumors." (PMID 38902237, 2024). "Thus, USP15 promotes tumor cell proliferation and tumor growth through maintaining TBX3 level and related downstream events." (PMID 38750011, 2024). "Next, we evaluated the effect of USP15 knockdown on tumor metastatic colonization in nude mice." (PMID 39164728, 2024). "Moreover, the expression level of USP15 remained low in xenograft tumor tissues of the knockdown group and was consistent with the trend of proliferation markers expression." (PMID 39164728, 2024). "Note that USP15 may contribute to multiple cellular functions, of which a majority may be irrelevant for tumor progression in HCC." (PMID 36900163, 2023). "These proteins level changes revealed the mechanism by which USP15 represses tumor growth." (PMID 36900163, 2023). "We confirmed the role of USP15 as a tumor suppressor in a mouse model." (PMID 36900163, 2023). "On the other hand, USP15 may act as an oncogene and a tumor suppressor in different contexts, including being an attractive therapeutic target." (PMID 37373211, 2023). "Overexpression of USP15 led to reduced tumor growth in a mouse model." (PMID 36900163, 2023). "We confirmed a high expression of USP15 by immunostaining of tumor tissue." (PMID 36900163, 2023). "In a mouse model, overexpression of USP15 correlated with slow tumor growth." (PMID 36900163, 2023). "USP15 has been shown to act as an oncogene or as a tumor-suppressing gene." (PMID 36900163, 2023). "Additionally, in our own cohort of 102 patients, we found expression of USP15 reduced in tumor tissue." (PMID 36900163, 2023). "USP15 promotes tumor cell invasion and proliferation in GBM." (PMID 36816802, 2023). "The localization of USP15 in tumor tissues was also nucleus, cytosol, or membrane." (PMID 35027535, 2022).
tumor (continued). "In addition, USP15 expression was positively correlated with immune infiltration, including immune score, mesenchymal score, and several tumor-infiltrating lymphocytes (TIL)." (PMID 36213818, 2022). "In such mice, Usp15 deficiency enhanced MDM2/NFATC2 pathway-dependent T-cell activation in vitro and a strong T-cell tumor infiltration in vivo with a major contribution of T-cell-mediated IFN-γ within the anti-tumor immune response." (PMID 35884430, 2022). "The results of this work may reflect the role of USP15 in tumor metastasis, providing an opportunity to assess the clinical relevance of USP15 for metastasis." (PMID 36213818, 2022). "As a tumor suppressor, USP15 suppresses the cell growth in glioblastoma by stabilizing HECTD120." (PMID 33771975, 2021). "We explore if USP15 can improve the anti-tumor function of tamoxifen in ERα+ BC cells." (PMID 33771975, 2021). "Tumor weight was lighter in USP15 shRNA-treated group than that of scramble shRNA-treated group." (PMID 33771975, 2021). "Furthermore, knockdown of BMI1 or USP15 inhibited the enhanced tumor growth by IL1R2 overexpression in vivo, and also inhibited the BTICs enrichment in the xenograft tumors." (PMID 31921558, 2020). "We recently discovered that USP15 controls stability of the RE1-silencing transcription factor (REST), a context-dependent tumour suppressor or oncogene, which is acutely degraded at mitosis before being rapidly replenished in early G1 in a USP15-dependent manner." (PMID 29429988, 2018). "Moreover, in vivo experiments indicated that USP15 silencing inhibited MM tumor growth and NF-κBp65 expression." (PMID 30459344, 2018). "Thus, the cellular outcome of USP15 activity likely depends on the specific protein complexes it forms, which may dictate whether USP15 acts in an oncogenic or tumor‐suppressive manner." (PMID 40762380, 2025). "Therefore, pathologically activated BRAF/MAPK signaling, possibly by BRAFV600E, initiates and promotes tumor development through transcriptionally elevating USP15 and protecting TBX3 from degradation, in addition to direct transcriptionally up-regulating TBX315." (PMID 38750011, 2024). "Notably, Usp15 in the primary tumor cells is under BRAF/MAPK pathway control." (PMID 38750011, 2024). "Therefore, we deleted Usp15 gene by crossing Usp15null mice with mPTC line (homozygotes of Usp15 deletion would be referred as mPTC/Usp15-/-, heterozygotes as mPTC/Usp15+/- in the following text) to determine the biological significance of Usp15 in endogenous tumor formation." (PMID 38750011, 2024). "Mice with USP15-deficient T cells were found to generate excessive IFN-γ, which up-regulated expression of PD-L1 and CXCL12, causing effector T-cell exhaustion alongside infiltration of Tregs and myeloid-derived suppressor cells (MDSCs) into tumours, which promoted tumour formation." (PMID 37503572, 2023). "Hence, USP15 may indeed have a tumor suppressive role that is targeted in a subset of GBM by deletion (11%), resulting in enhanced WNT pathway activity." (PMID 29299163, 2017). "In triple‐negative breast cancer (TNBC), ubiquitin‐specific protease 15 (USP15) (a deubiquitinating enzyme) stabilizes PARP1, enhancing BER capacity and promoting tumor cell proliferation." (PMID 40904702, 2025). "Among these, USP11—a deubiquitinating enzyme structurally and sequentially similar to USP4 and USP15—was notably overexpressed in the tumor tissues of 25 CRC patients, compared to USP4 and USP15." (PMID 41419456, 2025). "This study demonstrates the oncogenic role of USP15 in NSCLC, highlighting its contribution to tumor progression, chemoresistance, and RNA processing." (PMID 40762380, 2025). "We discovered that high expression of PUMA stabilizes FASN through USP15, forming a PUMA–USP15–FASN axis that promotes tumor progression and lipid accumulation." (PMID 40533456, 2025).
tumor (continued). "Compared to the high penetrance of tumor occurrence around 30 days in control mice, local PTC tumors were hardly formed in mPTC/Usp15-/- and mPTC/Usp15+/- mice." (PMID 38750011, 2024). "The clinical relevance is highlighted in that both USP15 and TBX3 highly correlates with BRAFV600E signature and poor tumor prognosis." (PMID 38750011, 2024). "These candidates included well-known PDAC tumor suppressor genes, such as Cdkn2a23, Rnf4324, Fbxw725 or NF226, as well as genes with poorly understood function, such as Usp15 and Scaf1." (PMID 38902237, 2024). "Ablation of USP15 increases TET2 binding to Cxcl9, Cxcl10, and Cxcl11 promoters, which trigger the production of IFN-γ chemokines and boosts tumor-infiltrating lymphocytes to improve the responsiveness to anti-PD-L1 treatment." (PMID 37658402, 2023). "In contrast, the deletion of USP15 enhances TET activity and tumor-intrinsic chemokines as well as infiltration and IFN-γ production from active T cells." (PMID 35884430, 2022). "Further experiments demonstrated that the MYEOV ceRNA sequestered miR-30c-2-3p from binding its targets TGFBR2 and USP15 mRNAs, which in turn leading to constitutive activation of TGF-β signaling and tumor progression in NSCLC." (PMID 30181549, 2019). "Mouse USP15 shares 75.5% sequence similarity with the mouse USP4, named Unp, which has been identified as a proto-oncogene able to promote tumor initiation when overexpressed in nude mice." (PMID 28245560, 2017). "By interacting with FASN and USP15, PUMA drives metabolic reprogramming and tumor growth." (PMID 40533456, 2025). "The observed decrease in colony formation ability and invasive potential upon USP15 knockdown suggested that USP15 functions as an oncogene rather than a tumor suppressor gene in NSCLC, promoting both tumor growth and metastatic potential." (PMID 40762380, 2025). "In triple‐negative breast cancer, USP15 stabilizes PARP1 through deubiquitination → enhances base excision repair (BER); ER/PR/HER2 deficiency → ↑USP15–PARP1 interaction → promotes tumor growth and survival." (PMID 40904702, 2025). "Although inhibition of USP15 expression did not effectively prevent tumor growth, USP15 knockdown indeed enhanced the antitumor effect of L-OHP, which was similar with the results of in vitro." (PMID 39164728, 2024). "Therefore, USP15 maintains TBX3 expression through physiological development and pathological tumor progression where both confine the differentiation progression, as the more USP15/TBX3, the less differentiation, and vice versa." (PMID 38750011, 2024). "In addition, USP8, USP15, USP9X, and USP18 can directly bind to PD-L1, stabilizing PD-L1 expression and promoting immune evasion by tumor cells." (PMID 39315102, 2024). "Upon orthotopic injection, Usp15 knock-out KC cells also formed allograft tumor faster than non-targeting control cells." (PMID 38902237, 2024). "We combined the 143 HCC genes with results of an experimental investigation to identify 225 pathways that may be related simultaneously to USP15 and HCC (tumor pathways)." (PMID 36900163, 2023).
tumor (continued). "Patients with tumor tissue of negative or weak staining were assigned to the group low expression of USP15 (n = 76)." (PMID 36900163, 2023). "Depletion of USP15 increased, while overexpression of USP15 reduced the resistance of CML cells to Imatinib, suggesting that USP15 may function as a tumor suppressor in CML and involve in Imatinib resistance." (PMID 31952546, 2020). "Independent of its protein-coding capacity, MYEOV transcript exerts its pro-metastatic function via abrogating the suppression of TGFBR2 and Ubiquitin specific protease 15 (USP15) expression by miR-30c-2-3p, leading to constitutive activation of TGF-β signaling and tumor progression in NSCLC." (PMID 30181549, 2019). "Additionally, knockdown of USP15 in GB, which stabilizes the type I TGF-β receptor, decreases the oncogenic capacity of patient-derived tumor cells in an orthotopic mouse model." (PMID 23667531, 2013). "Tumor and non-tumor tissue samples were immunochemically stained for USP15." (PMID 36900163, 2023). "The correlation coefficient between USP15 and SMAD7 (R = 0.11, p < 0.05) The Smad protein is the first detected kinase substrate of the TGF-β receptor, so we hypothesize that USP15 in BRCA most likely plays a role in promoting tumor development and metastasis via the TGF-β/smad signaling pathway." (PMID 36213818, 2022). "Together these data indicate that the short isoform has no tumor suppressive functions or alters the response to PARP inhibition and that Scaf1’s tumor suppressive function is at least in part routed by regulating the expression of full-length Usp15." (PMID 38902237, 2024).
infection (6 papers, 2020 to 2025). The state of being infected such as from the introduction of a foreign agent such as serum, vaccine, antigenic substance or organism. "hPASMCs were next subjected to a wound healing assay after infection, and USP15 deficiency exhibited an inhibitory effect on the migration of the hypoxia-stimulated cells." (PMID 36635430, 2023). "Loss of functional USP15 was achieved in hPASMCs by Ad-hUSP15-sh infection." (PMID 36635430, 2023). "The upper USP15 band shifts up with infection and shifts back to mock levels with the addition of lambda phosphatase, further confirming that the mobility shift is due to phosphorylation." (PMID 40824090, 2025). "Despite the lower expression due to the gD promoter, lentivirus-delivered UL12 was able to fully rescue the phosphorylation of USP15 during infection with AN-1." (PMID 40824090, 2025). "We then quantified the total USP15 intensity per nucleus and observed a significant decrease in USP15 intensity during infection of shUSP15 cells compared to shGFP cells." (PMID 40824090, 2025). "One model is that USP15 stabilizes UL12 during infection by removing ubiquitin signals that would lead to UL12 degradation through the proteasome." (PMID 40824090, 2025). "USP15 was also recruited to the nucleus during KOS infection in the presence of the viral helicase/primase inhibitor." (PMID 40824090, 2025). "Loss of USP15 resulted in a 10-fold reduction in the amount of virus produced at 24 hours, similar to what was observed with low MOI infections of HFF cells expressing shUSP15." (PMID 40824090, 2025). "Depletion of USP15 with shRNA treatment caused a significant reduction in both virus yield, probability of plaque formation, and the rate of DNA synthesis, suggesting that USP15 activity promotes infection and DNA replication." (PMID 40824090, 2025). "We demonstrated that UL12 interacts directly with USP15, and that UL12 is necessary and sufficient for USP15 localization to the nucleus and sites of DNA replication during infection." (PMID 40824090, 2025). "This nuclear localization was greatly reduced during infection with AN-1, although there is still detectable USP15 in the nucleus." (PMID 40824090, 2025). "Knockdown of USP15 resulted in a 10-fold reduction in the amount of virus produced at 24 hours post-infection." (PMID 40824090, 2025). "HSV-1 DNA replication activates the ATM kinase, so we hypothesized that USP15 would be phosphorylated during infection." (PMID 40824090, 2025). "Indeed, we observed phosphorylation of USP15 as early as 2 hours post-infection by mobility shift in SDS-PAGE." (PMID 40824090, 2025). "Since ATM is activated during KOS infection (20, –, 22) and USP15 is required for efficient HSV DNA replication, we hypothesized that USP15 would also be phosphorylated." (PMID 40824090, 2025). "USP15 was predominantly upregulated in the hypoxia-treated cells and downregulated after infection." (PMID 36635430, 2023). "USP15 also regulates the stability of UL12 in both transfection-based experiments and during infection." (PMID 40824090, 2025). "The western blotting analysis of the probe-reacted deubiquitinases was used as a validation, where the level of USP14, USP15, OTUD6B and USP47 was diminished during infection with Y. enterocolitica at 18 hpi." (PMID 37026055, 2023). "We also did not observe any significant change in the amount of total USP15 during infection with KOS." (PMID 40824090, 2025). "Since UL12 is required for the nuclear localization of USP15 during infection, we hypothesized that UL12 might be required for USP15 phosphorylation." (PMID 40824090, 2025). "The USP15 mobility shift did not occur during infection with AN-1, suggesting that UL12 is required for the phosphorylation." (PMID 40824090, 2025). "Similarly, we also observed a correlation between USP15 and ICP8 during KOS infection in the presence of the viral helicase/primase inhibitor." (PMID 40824090, 2025).
infection (continued). "Finally, we observed that USP15 is phosphorylated early during infection, and the phosphorylation is independent of ATM or DNA synthesis." (PMID 40824090, 2025). "Immunofluorescence analysis of ICP4 in plaque experiments revealed that plaques were much smaller in the absence of USP15 and infection did not spread to neighboring cells, likely explaining the reduced probability of plaque formation observed with crystal violet at 3 days post-infection." (PMID 40824090, 2025). "First, Vero cells expressing shRNA targeting USP15 or a negative control protein, GFP, were infected with KOS at an MOI of 3 PFU/cell and analyzed by immunoblotting at 6 hours post-infection." (PMID 40824090, 2025).
adenocarcinoma (2 papers, 2022). A common cancer characterized by the presence of malignant glandular cells. "Some adenocarcinoma tissues expressed USP15 strongly, whose location in cells were variable in nucleus, cytosol, or membrane." (PMID 35027535, 2022).
blood cancer (1 paper, 2020). "The functional interaction between USP15 and FUS in blood cancer cells suggests that USP15 regulates DDR pathways in context-dependent manner." (PMID 33378683, 2020).
USP15 also shares sentences with these, for which no sentence is quoted: bacterial infection (2 papers); lung squamous cell carcinoma (2); pancreatic ductal adenocarcinoma (2); acute leukemia (1); acute lymphoblastic leukemia (1); cervical squamous cell carcinoma (1); cholangiocarcinoma (1); chronic obstructive pulmonary disease (1); diabetic nephropathy (1); endometrial cancer (1); esophageal adenocarcinoma (1); esophageal cancer (1); experimental autoimmune encephalomyelitis (1); gastric adenocarcinoma (1); Gliosis (1); Hashimoto thyroiditis (1); head and neck squamous cell carcinoma (1); hematological diseases (1); Huntington disease (1); invasive breast carcinoma (1); kidney cancer (1); lobular breast carcinomas (1); lymphoma (1); Myelodysplasia (1); myeloid leukemia (1); nonalcoholic fatty liver disease (1); nonalcoholic steatohepatitis (1); ovarian serous cystadenocarcinoma (1); ovarian tumors (1); pemphigus foliaceus (1).
A further 5 diseases each share a sentence with USP15 in 1 paper.